IL31 (interleukin 31)
Diseases named in the same sentence as IL31 in open-access papers (continued):
Sharing a sentence is not in itself a finding about the gene and the disease.
Pruritus (continued). "A recent study found that IL-31 is not directly linked to inflammation or atopic status in CSU; however, its expression is influenced by several factors including disease severity and pruritus." (PMID 38541037, 2024). "Our findings suggest that various non-histaminergic mediators such as tryptase and IL-31 could be explored as novel therapeutic targets for managing pruritus in MF patients." (PMID 39068637, 2024). "Interestingly, a recent study demonstrated that IL-31 is only essential for the induction of pruritus, not for activating DCs or inducing inflammation in the contact dermatitis murine model induced with a hapten." (PMID 37686326, 2023). "Moreover, there was a significant difference (p < 0.001) in IL-31 serum levels between HD patients with and without pruritus and healthy controls (p < 0.001 and p = 0.019, respectively)." (PMID 35324695, 2022). "Also, the observation that baseline IL-31 did not correlate with baseline VAS score indicates that IL-31 does not correlate with pruritus severity." (PMID 35036239, 2022). "Still, in 69% of patients that had reported (moderate to severe) pruritus IL31 could not be detected." (PMID 34027133, 2021). "IL-31/IL-31RA interaction activates signal transduction pathways leading to expression and release of various chemokines, proinflammatory cytokines, regulation of cell proliferation and stimulation of DRG neurons that play important role in pruritus induction and inflammatory diseases." (PMID 33681256, 2021). "However, our observations do not support a prominent role for IL31 in the pathogenesis of pruritus and disease activity in CTCL patients and further studies elucidating crucial mechanisms in CTCL pruritus are highly warranted." (PMID 34027133, 2021). "Thus, it is conceivable that FK506 did not target the IL-31 pathway, resulting in weak therapeutic effects on pruritus, which is in line with previous study which showed that IL-31-induced scratching behavior is not inhibited by treatment with FK506." (PMID 33539470, 2021). "Serum IL-31 concentration in patients receiving maintenance hemodialysis has been reported to be higher in those with pruritus than in those without pruritus; this suggests that serum IL-31 concentration in blood may affect or predict efficacy." (PMID 33754202, 2021). "While acute high dose UVB is capable of transiently increasing IL-31 expression in the skin, UVA-1 phototherapy with suberythemogenic therapeutic doses for 6 weeks reduced IL-31 mRNA expression to levels close to normal, beside reducing atopic eczema and pruritus." (PMID 30560129, 2018). "Interestingly, some studies have suggested that there is no general relationship between IL-31 protein expression and pruritus in Th2 weighted diseases." (PMID 27294147, 2016). "Although tumor cells in MF/SS exhibit similar cytokine profile with AD and both are characterized with pruritus, the analysis of the IL-31 pathway in MF/SS patients regarding serum levels as well as receptor expression does not suggest a central role of IL-31 in MF/SS pathogenesis." (PMID 27294147, 2016). "In addition, increased serum IL-31 levels were noted in primary cutaneous T-cell lymphomas (CTCL) and it was even suggested that pruritus in CTCL may be related to IL-31." (PMID 25756056, 2015). "However, similarly to our findings in LP, these authors also did not observe any relationship between pruritus intensity and IL-31 level in patients with psoriasis." (PMID 25756056, 2015). "Hence, results of the present study indicate that the studied cytokines- IL-13, IL-31 and TNF-α, have key role in the pathogenesis of canine AD and expression of IL-13 and TNF-α genes in atopic dogs might be down-regulated with increased severity of pruritus." (PMID 34075152, 2021). "However, in 69% of all patients that reported moderate to severe pruritus in our cohort, IL31 could not be detected, questioning an important role for IL31 related pruritus in our CTCL patients." (PMID 34027133, 2021).
Pruritus (continued). "However, we observed a similar trend in SS, with higher levels of IL-31, GRP, and CCL24 in those with current pruritus compared to those without." (PMID 39068637, 2024). "The number of the IL‐31 positive cells in the dermis did not correlate with pruritus severity;39 however, protein levels of IL‐31 receptors, IL‐31RA and OSMR, in both epidermis and dermis, were increased and correlated with pruritus severity." (PMID 36477831, 2023). "Researchers did not establish with certainty whether IL-31 concentration is correlated with CTCL progression or/and pruritus." (PMID 34948183, 2021).
atopic dermatitis (145 papers, 2007 to 2026). "TMEM184B loss in DRG neurons causes disruption of sensation of interleukin-31, a key cytokine involved in atopic dermatitis (eczema) that is detected exclusively by SST + neurons." (PMID 37730546, 2023). "Accompanying the increase in leukocyte infiltration was the upregulation of the atopic dermatitis-associated pruritogenic ‘itch’ factor IL-31." (PMID 35265075, 2022). "Humanized antibodies against IL-13, IL-4, and IL-31 proved effective in treatment of itch-associated atopic dermatitis but remain to be validated in chronic itch." (PMID 36077340, 2022). "In BALB/c mice, the absence of WASp resulted in epidermal barrier disruption with tight junction aberrancies, increased transepidermal water loss (TEWL) and upregulation of the atopic dermatitis (AD) associated factor IL-31." (PMID 35265075, 2022). "Via phosphorylation of JAK1/2 and PI3K/Akt and the consequent activation of the STAT pathway (STAT3 and STAT5), IL-31 causes skin inflammation and proceeds to the dysregulation of the immunomodulatory proteins in atopic dermatitis." (PMID 35742951, 2022). "Skin alteration were associated to IL-31 and in every disease the immune system acted a main role: atopic dermatitis (AD), allergic contact dermatitis, prurigo nodularis, and chronic urticaria are some examples." (PMID 34118946, 2021). "An over expression IL-31 in transgenic mice has been attributed to initiation of various hallmark signs of atopic dermatitis for instance increased inflammatory cells infiltration into the cutaneous tissue, marked pruritus, alopecia and cutaneous lesions." (PMID 34075152, 2021). "Recently, IL-31 and IL-4 have been implicated in intractable itch associated with atopic dermatitis." (PMID 32152328, 2020). "Plenty of studies have demonstrated the pathogenic role for IL-31 in atopic dermatitis and allergic asthma." (PMID 32528891, 2020). "Since IL-31 is closely linked to the itch in atopic dermatitis, this pushed us to investigate the effects of apigenin in alleviating itch in an atopic dermatitis itch model and to investigate the expression levels of IL-31 in the skin of the mice." (PMID 30987029, 2019). "IL-31 has been implicated in several inflammatory diseases, including atopic dermatitis, pruritus (especially in atopic dermatitis), inflammatory bowel diseases, and skin and airway hypersensitivity." (PMID 30987029, 2019). "Atopic dermatitis has also been linked to variants within the genes encoding the T2 pathway-associated cytokines/cytokine receptors IL-4, IL-13, IL-4RA, and IL-31 and associated downstream molecules like STAT6 and GATA3." (PMID 31028434, 2019). "Since IL-31 is strongly associated with itch in atopic dermatitis, we investigated the effects of apigenin on compound 48/80-induced expression of IL-31 mRNA and protein in the dorsal skin of the mice." (PMID 30987029, 2019). "In coincident with IL-31 receptor distribution, IL-31 was already identified to be associated with immune-dysfunction diseases such as atopic dermatitis, SLE, and asthma." (PMID 28572699, 2017). "Investigation of IL-31 transgenic mice has shown that overexpression of IL-31 results in the development of atopic dermatitis (AD)-like lesions, and that IL-31 expression is highly associated with Th2-skewed diseases." (PMID 28428802, 2017). "Here we show that CD4+ T cells from DOCK8-deficient mice produce large amounts of IL-31, a major pruritogen associated with atopic dermatitis." (PMID 28067314, 2017). "Overexpression of IL-31 in T cells causes severe inflammation, with histological features similar to skin lesions of patients with atopic dermatitis." (PMID 27556734, 2016). "The function of IL-31 is not fully understood, but this cytokine has been associated with atopic dermatitis, Crohn disease, and allergic asthma and rhinitis." (PMID 26352837, 2015).
atopic dermatitis (continued). "The overexpression of IL-31 in transgenic mice caused alopecia and chronic pruritus, which led to development of skin lesions similar to those observed in atopic dermatitis." (PMID 23108364, 2013). "Therefore, higher levels of IL-31 in serum and CSF in these dogs are more likely the result of a possible, undiagnosed underlying atopic dermatitis and less likely due to syringomyelia." (PMID 37993920, 2023). "Upregulation of IL-31 has been shown to cause an atopic dermatitis-like phenotype in mouse models." (PMID 36983094, 2023). "In addition, histamine receptor 4 is upregulated on CD4-positive T cells from patients with atopic dermatitis, which is associated with the induction of IL-31, a major mediator of itch." (PMID 36552866, 2022). "On another note, even the polymorphisms of IL-31 haplotypes could lead to different manifestations of atopic eczema, suggesting that some subtypes of this cytokine could lead to better or worse clinical pictures." (PMID 35742951, 2022). "Furthermore, in patients with atopic dermatitis, elevated IL-4 and IL-31 levels stimulate sensory nerves and cause itching." (PMID 34959939, 2021). "Several variants of the IL31 gene have been reported in association with atopic dermatitis." (PMID 33401724, 2021). "It was initially identified as being associated with the promotion of atopic dermatitis, where increased levels of IL-31 levels have been found and IL-31 induced the expression of proinflammatory cytokines and chemokines in a human bronchial epithelial cell line." (PMID 30647024, 2019). "Central mediators of this axis include IL-4, IL-13, and IL-31, which play crucial roles in driving inflammation in atopic dermatitis." (PMID 41002407, 2025). "Over expression of IL-31 has been detected in other itchy dermatoses like atopic dermatitis and prurigo nodularis." (PMID 41325491, 2025). "IL-31 is markedly elevated in pruritic skin diseases; in humans, serum IL-31 levels correlate with the severity of atopic dermatitis." (PMID 41303472, 2025). "This review, therefore, aims to assess the IL-31/IL-33 axis in atopic dermatitis, highlight existing uncertainties, and emphasize the need to develop biomarker and endotype-based therapeutic strategies targeting this pathway." (PMID 41155460, 2025). "Inflammatory dermatoses such as atopic dermatitis and prurigo nodularis often feature elevated levels of interleukin-31 (IL-31), a pruritogenic cytokine." (PMID 40142630, 2025). "The IL-31 neuroimmune axis plays a key role in the development of chronic itch characteristic of atopic dermatitis." (PMID 41002407, 2025). "The immunology of chronic prurigo shows similarities with atopic dermatitis due to the involvement of IL-4 and IL-13, IL-22, and IL-31." (PMID 38493053, 2024). "It has been reported that IL‐17, IL‐31 and IgE concentrations are significantly increased in dogs with atopic dermatitis." (PMID 38648253, 2024). "In conclusion, N. benthamiana plant-cell-based platform feasibility was illustrated for the rapid expression and purification of the anti-Il-31 IgG designed for the treatment of canine atopic dermatitis." (PMID 38932349, 2024). "Histamine-independent pathways, which involve cytokines such as interleukin-31 (IL-31) and proteases, play a role in chronic and systemic diseases like atopic dermatitis and chronic kidney disease." (PMID 39771213, 2024). "Itching in atopic dermatitis has several mediators of dysregulated inflammation, including histamine and its receptors, IL-31, IL-1, and others." (PMID 38731996, 2024). "Recently published research has found that FXR agonists such as OCA and cilofexor induce hepatic expression and secretion of the pruritogenic cytokine Interleukin-31 (IL-31), a large player in atopic dermatitis." (PMID 38664391, 2024).
atopic dermatitis (continued). "The IL-31 were measured in archived samples (52 serum and 35 CSF samples) of dogs with syringomyelia (n = 48), atopic dermatitis (n = 3) and of healthy control dogs (n = 11) using a competitive canine IL-31 ELISA." (PMID 37993920, 2023). "Mean serum IL-31 level in dogs with syringomyelia was 150.1 pg/ml (n = 39), in dogs with atopic dermatitis 228.3 pg/ml (n = 3) and in healthy dogs 80.7 pg/ml (n = 10)." (PMID 37993920, 2023). "The keywords selected for our searching process were “dysbiosis”, “IL-31”, “IL-33”, “IL-33/31 axis” and “microbiota” combined with “atopic dermatitis” and “psoriasis”." (PMID 37509136, 2023). "Wakayama Medical University has submitted a patent (WO2013168829A1) for a monoclonal antibody against OSMRβ designed to inhibit both OSM and IL-31 induced inflammation in patients with atopic dermatitis." (PMID 37841259, 2023). "Interleukin-31 is a cytokine that has been shown to be elevated among other things in dogs with atopic dermatitis and dogs with a typical phenotype of inflammation (Th2-mediated) in previous studies." (PMID 37627467, 2023). "IL-4, a significant atopic dermatitis mediator, stimulates IL-31 production in human lymphocytes via activating the JAK-STAT signaling pathway." (PMID 36983094, 2023). "Of interest, among all ILs tested, IL-8, IL-12 and IL-31 seem to be involved in several inflammatory skin conditions, such as psoriasis, atopic dermatitis and itch, as well as in innate and adaptive immunity." (PMID 36769042, 2023). "Interleukin 31 is involved in the pathogenesis of chronic inflammatory skin disorders, including atopic dermatitis, allergic contact dermatitis, and mastocytosis." (PMID 37632245, 2023). "Lokivetmab, a caninized anti-IL-31 monoclonal antibody, is another example of canine therapeutic antibodies, which reduces pruritus in dogs with atopic dermatitis." (PMID 36701408, 2023). "The mean IL-31 level in patients with SRMA was mildly higher than in patients with atopic dermatitis (p = 0.8135) and MUO (p = 0.7618), but this difference was not statistically significant." (PMID 37627467, 2023). "Of the three dogs with atopic dermatitis (group B), two dogs had higher IL-31 levels in serum than healthy control dogs." (PMID 37993920, 2023). "Despite this need, there has been less focus on pruritus in the specialized literature that studies chronic urticaria, the symptom being more pathognomonic for atopic dermatitis, which is why IL-31 was also studied further in the context of this condition." (PMID 37762898, 2023). "Lokivetmab is a caninized IL-31 monoclonal antibody which was approved in 2017 by the European Medicines Agency for the treatment of canine atopic dermatitis." (PMID 37509136, 2023). "It effectively decreases serum markers of atopic dermatitis inflammation in a dose-dependent manner, including interleukin-31 (IL-31), thymus and activation-regulated chemokine (TARC), and high-sensitivity C-reactive protein (hsCRP)." (PMID 37661221, 2023). "In atopic dermatitis pruritus is mediated among others via elevated Interleukin-31 (IL-31) which is produced by T-helper (Th) 2 cells." (PMID 37993920, 2023). "Increased interleukin-31 (IL-31) is found in many itchy conditions including atopic dermatitis and cutaneous T-cell lymphoma, and is thought to contribute to itch sensation through modulation of TRPA1." (PMID 36613861, 2022). "Another target is IL-31, for which the antibody nemolizumab is currently under investigation for the treatment of moderate-to-severe atopic dermatitis." (PMID 36552866, 2022). "Among its activities in this disease, IL-31 also promotes epidermal-cells’ proliferation and thickening of the skin via skin remodeling, during the chronic Th-1-mediated phase of atopic dermatitis." (PMID 35742951, 2022). "Interleukin 31 belongs to the IL-6 superfamily, and it is an itch mediator already studied in several diseases, comprising atopic dermatitis, allergic pathologies, and onco-hematological conditions." (PMID 35742951, 2022).